COL3A1 (collagen type III alpha 1 chain)
Diseases named in the same sentence as COL3A1 in open-access papers (continued):
Sharing a sentence is not in itself a finding about the gene and the disease.
neurofibroma (2 papers, 2018 to 2025). An intraneural or extraneural neoplasm arising from nerve tissues and neural sheaths. "Such depletion of COL3A1 also suppressed the growth of neurofibroma cells and DFAT cells derived from NF1 patients." (PMID 29666462, 2018). "We established the tranilast-resistant neurofibroma cells derived from patient 1 that had been exposed to 250 μM tranilast for 20 days, and we found that the abundance of COL3A1 and SOX2 mRNAs was increased in the tranilast-resistant neurofibroma cells." (PMID 29666462, 2018). "The knockdown of COL3A1 markedly suppressed the proliferation of tranilast-resistant neurofibroma cells, suggesting that COL3A1 is a major ECM component affecting the proliferation of neurofibromin-deficient cells, however, the depletion of COL3A1 did not increase tranilast sensitivity." (PMID 29666462, 2018). "Finally, we found that the expression of COL3A1 and SOX2 was increased in tranilast-resistant neurofibroma cells, suggesting that the encoded proteins may give rise to resistance to tranilast treatment." (PMID 29666462, 2018). "Knockdown of type III collagen (COL3A1) also suppressed the proliferation of neurofibroma cells, whereas expression of COL3A1 and SOX2 was increased in tranilast-resistant cells, suggesting that COL3A1 and the transcription factor SOX2 might contribute to the development of tranilast resistance." (PMID 29666462, 2018).
pterygium (2 papers, 2019 to 2021). A wedge-shaped fibrovascular lesion arising from the bulbar conjunctiva and extending to the cornea. "It indicated miR-29b-3p might be implicated in the development of pterygium and the collagen family, including COL3A1 and COL4A1 regulated by miR-29b-3p and associated with PI3K-Akt signalling pathway, might serve roles in the pathogenesis of pterygium." (PMID 31341891, 2019). "MiR-29b-3p and collagen family (COL4A1 and COL3A1) might be new treatment target in pterygium." (PMID 31341891, 2019). "FN1 and the collagen family, including COL1A1, COL3A1, and COL4A1, were the components of ECM, involved in the fibrotic type of fibrosis and might be a group of significant genes in pterygium." (PMID 31341891, 2019).
rectal cancer (2 papers, 2021 to 2023). A primary or metastatic malignant neoplasm that affects the rectum. "We performed qRT-PCR for GUCA2A and COL3A1 in colon and rectal cancer." (PMID 37816854, 2023). "Besides, the expression level of COL3A1 can predict the efficacy of neoadjuvant therapy in rectal carcinoma." (PMID 35047627, 2021).
renal carcinoma (2 papers, 2023 to 2025). A carcinoma arising from the epithelium of the renal parenchyma or the renal pelvis. "EMP1 +/COL3A1 + fibroblasts are implicated in the bone metastasis of renal cancer and are associated with the activation of EMT genes and the wingless-type MMTV integration site family (WNT) signaling pathway." (PMID 41035074, 2025). "In renal cancer bone metastasis samples, fibroblasts exhibit increased expression of COL3A1 and EMP1, indicating their involvement in bone metastasis." (PMID 41035074, 2025). "In our results, we also found the involvement of EMP1+/COL3A1+ fibroblasts during the BoM process in breast and renal cancer, which is consistent with previous findings." (PMID 38187400, 2023). "Among different subgroups in renal cancer scRNAseq data, significant correlations between EMP1/COL3A1 and four EMT genes (VIM, SNAI2, TWIST1, and CTNNB1) were found in c9 fibroblasts." (PMID 38187400, 2023).
scleroderma (2 papers, 2013 to 2023). Scleroderma is a rare autoimmune connective tissue disorder characterized by abnormal hardening of the skin and, sometimes, other organs. "We demonstrated that both inflammation-driving subtypes, CCL19+ and SPARC+COL3A1+/FAP+THY+, are present in scleroderma, possibly promoting inflammation through chemotaxis and enhanced leucocyte infiltration." (PMID 37443817, 2023).
serous ovarian cancer (2 papers, 2015 to 2024). "Our data also indicated that both EDNRA and COL3A1 showed significant prognostic properties in patients diagnosed with high-grade serous ovarian cancer." (PMID 26100469, 2015). "A related study has shown that COL3A1 and COL5A2 were top hub genes related to the stage of serous ovarian cancers." (PMID 39518852, 2024).
silicosis (2 papers, 2018 to 2021). Silicosis is a respiratory disease caused by breathing in (inhaling) silica dust. "Moreover, the mice with silicosis following treatment of miR‐205‐5p agomir showed upregulated expression patterns of Col1a1, Col3a1 and LC3, while this upregulation was annulled by Lenti‐E2F1, Lenti‐SKP2 or siBeclin1." (PMID 34428336, 2021). "Compared with healthy controls, silicosis patients had remarkably higher plasma concentrations of matrix metalloproteinase-2 (MMP-2), matrix metalloproteinase-9 (MMP-9), collagen alpha-1(I) protein (COL1A1), and collagen alpha-1(III) protein (COL3A1) (all p < 0.05)." (PMID 30558126, 2018).
skin aging (2 papers, 2015). The gradual irreversible changes in structure of skin that occur as a result of the passage of time.. "Indeed, we detected a set of metallo-proteinases (MMP2, MMP14), collagens (e.g. COL6A1, COL3A1, COL5A1 and others) and elastin (ELN), which showed a significant longitudinal change in expression in addition to being closely correlated to skin aging." (PMID 25977295, 2015).
systemic sclerosis (2 papers, 2015 to 2025). A chronic disorder, possibly autoimmune, marked by excessive production of collagen which results in hardening and thickening of body tissues. "Recently, Col3a1 was suggested to play a role in the causation of the tight skin phonotype in a mouse model tight skin 2 (Tsk2/+), for systemic sclerosis (SSc)." (PMID 26151842, 2015). "Notably, in systemic sclerosis (SSc), TGF-β drives fibroblast transition via Smad signaling, whereas baricitinib’s EGFR affinity downregulates COL1A1/COL3A1 to restore collagen density in skin models." (PMID 41585231, 2025).
Ureteral obstruction (2 papers, 2018 to 2019). Obstruction of the flow of urine through the ureter. "We measured transcript levels of Col1a1 and Col3a1 in the WT and Il17ra−/− kidneys following ureteral obstruction." (PMID 30405320, 2018). "Otherwise, many of these genes, such as Agt, Ccl12, Col3a1, Dcn, Itgb6, and Thbs2, were temporarily changed in these MSLCs expanded from the left kidney at only 7 days after ureteral obstruction, but the changes of Ccl3 and Cxcr4 were constantly observed during the 14 days of follow-up." (PMID 30949209, 2019).
Vestibular schwannoma (2 papers, 2021 to 2025). A vestibular schwannoma (also known as acoustic neuroma, acoustic neurinoma, or acoustic neurilemoma) is a benign, usually slow-growing tumor that develops from the VIIIth cranial nerve supplying the inner ear. "Collagen, COL1A1 and COL3A1, were also overrepresented in our analysis and recently shown to be associated with recurrence of vestibular schwannoma after radiation therapy." (PMID 40585242, 2025).
Acidosis (1 paper, 2022). Abnormal acid accumulation or depletion of base. "Additionally, the top seven nodes of the “Acidosis” network were present among the top ten nodes of “Acidosis and Bone metastasis”: COL1A1, COL3A1, COL4A1, COL4A2, ITGB3, THBS2, and ITGA11." (PMID 35159353, 2022).
acrogeria (1 paper, 2017). A congenital skin condition characterized by premature aging, more especially in the form of unusually fragile, thin skin on the hands and feet. "COL3A1 missense variants in residues 652–925 have been reported more often with acrogeria." (PMID 28704418, 2017).
Bowen’s disease (1 paper, 2022). "Furthermore, the relative expression levels of TNC, FSCN1, SERPINB1 in the Bowen disease were also significantly increased, while the COL3A1 were also significantly decreased relative to the healthy control." (PMID 36085041, 2022). "We found the proteins expressed levels of COL3A1 and COL1A1 were significant decreased in CSCC relative to Bowen disease according to Western blot results." (PMID 36085041, 2022). "And next, among 20 proteins, 8 proteins (TNC, FSCN1, SERPINB1, ACTN1, RAB31, COL3A1, COL1A1 and CD36) expressed levels showed significant differences between CSCC and Bowen disease." (PMID 36085041, 2022). "Besides, the proteins of TNC, FSCN1, SERPINB1, ACTN1 and RAB31 in CSCC were significantly up-regulated, while COL3A1, COL1A1 and CD36 were significantly down-regulated relative to Bowen disease in proteomics results." (PMID 36085041, 2022).
brain cancer (1 paper, 2012). A primary or metastatic malignant neoplasm affecting the brain. "In reviewing the involvement of these genes with cancers in previous studies, hint for pan-cancer marker was surfaced as the expression of the extracellular matrix protein COL3A1 gene in brain cancer and angiofibroma was elevated." (PMID 23282184, 2012).
brain malformations (1 paper, 2012). "Based on the previous finding that mutations in COL3A1 cause type IV EDS, our study indicates a possible common pathological pathway linking connective tissue diseases and brain malformations." (PMID 22235340, 2012).
cardiac interstitial fibrosis (1 paper, 2023). "In line with cardiac interstitial fibrosis, the LV mRNA expression levels of the collagens I (Col1a1) and III (Col3a1) were increased in mice with TAC (as compared with sham)." (PMID 37227779, 2023).
cervical squamous cell carcinoma (1 paper, 2023). A squamous cell carcinoma arising from the cervical epithelium. "POSTN + fibroblasts showed high expression levels of several ECM remodeling genes (MMP11, CTHRC1, COL1A1, COL1A2, COL3A1, COL10A1, and COL11A1) and enriched signatures of ECM, which were consistent with the previously reported matrix CAFs (mCAFs) in cervical squamous cell carcinoma (CESC)." (PMID 37833788, 2023).
Charcot-Marie-Tooth disease type 1A (1 paper, 2019). Charcot-Marie-Tooth disease type 1A (CMT1A) is a type ofinherited neurological disorder that affects the peripheral nerves. "Muscle biopsy and genetic testing regarding Charcot-Marie-Tooth disease type 1A (CMT1A), Friedrichs ataxia (trinucleotide repeat in FXN), Loeys-Dietz syndrome (TGFBR1, TGFBR2) and Ehler Danlos syndrome type IV (COL3A1) were all normal as well as the karyotype of lymphocytes (46,XX)." (PMID 31053103, 2019).
cobblestone lissencephaly (1 paper, 2012). "It is possible that mutations in both alleles of COL3A1 associate with a lethal form of cobblestone lissencephaly similar to WWS." (PMID 22235340, 2012).
colon adenocarcinoma (1 paper, 2023). "Also, the survival analysis revealed that the high expression of COL3A1 has a not-significant relation with the low survival rate of colon adenocarcinoma and rectal adenocarcinoma patients." (PMID 37816854, 2023).
congestive heart failure (1 paper, 2021). Failure of the heart to pump a sufficient amount of blood to meet the needs of the body tissues, resulting in tissue congestion and edema. "The expression of miR29b decreased and the expression of miR29b ECM target-genes collagen-1A1 (COL1A1), collagen-3A1 (COL3A1) increased significantly in congestive heart failure (CHF) atrial fibroblasts." (PMID 35127848, 2021).
coronary artery aneurysms (1 paper, 2025). "Although spontaneous coronary artery dissections have been reported in patients with COL3A1 variants and without a diagnosis of vEDS, this article presents a novel case of coronary artery aneurysms and ectasias associated with a COL3A1 variant." (PMID 39996803, 2025). "Although each formation is similar in pathophysiology, this report serves as a novel finding of coronary artery aneurysms and ectasias associated with a COL3A1 variant in a patient who does not meet clinical criteria for vEDS." (PMID 39996803, 2025).
diastolic heart failure (1 paper, 2025). Heart failure caused by abnormal myocardial relaxation during diastole leading to defective cardiac filling. "An elevated Col1a1/Col3a1 ratio has been implicated in diastolic heart failure in DCM." (PMID 39592912, 2025).
diffuse large B-cell lymphoma (1 paper, 2020). "Finally, certain lymphoproliferative diseases are also associated with expression of COL6A1, COL18A1, MMP3 and TIMP1, and a subset of patients with diffuse large B cell lymphoma and adverse prognosis show decreased expression of POSTN, SPARC, COL1A1, COL3A1,CSTK, MMP9 and LAMB3." (PMID 33379263, 2020).
Disc Degeneration (1 paper, 2021). "Besides, RPL8 regulates the protein synthesis process of Disc Degeneration (DD), suggesting that COL3A1 might be used for the diagnosis and treatment of DD." (PMID 33635875, 2021).
Dupuytren contractures disease (1 paper, 2013). "The in silico functional analysis revealed that COL3A1 was associated with the response to the collagenase from Clostridium histolyticum, which comprises a treatment approved for progressive Dupuytren contractures disease (PDCD)." (PMID 23483937, 2013).
dysplasia (1 paper, 2012). A usually neoplastic transformation of the cell, associated with altered architectural tissue patterns. "However, there is one reported case of recessive type IV EDS with homozygous mutation in COL3A1 gene and a diffuse cortical dysplasia, which was most prominent frontally." (PMID 22235340, 2012).
echinococcosis (1 paper, 2022). A parasitic infection caused by tapeworm larvae of Echinococcus. "Mice infected with echinococcosis were also found to show higher COL1A1 and COL3A1 expression levels in the hepatic tissue." (PMID 36034715, 2022).
endometrioid carcinoma (1 paper, 2018). "Likewise, the endometrioid carcinoma revealed subpopulations of cells with high intensity score (red arrow), moderate (green arrow), and mild (purple arrow) intensity scores, and finally cells with no COL3A1 expression (black arrow)." (PMID 30583585, 2018).
enteritis (1 paper, 2016). Inflammation of the small intestine. "The average COL3A1 level (21.83 ng/mL) in the enteritis group was similar to the normal group, after excluding an extreme value." (PMID 26741506, 2016). "Plasma COL3A1 of the CRC patients (n = 86), but not enteritis (n = 21) and polyps (n = 3) patients, was significantly higher than that of the healthy donors (n = 68) (unpaired Student's t test, p = 1.3E-10)." (PMID 26741506, 2016).
fibrosarcoma (1 paper, 2023). A malignant mesenchymal fibroblastic neoplasm affecting the soft tissue and bone. "Notable, among these fusions are in-frame fusions of the collagen genes (exon 6 COL1A2, exon 20 COL1A2 and exon 35 COL3A1) with exon 2 of PDGFB in tumors of the H2 fibrosarcoma cluster which was associated with extracellular matrix and G-protein coupled receptor signaling pathways." (PMID 37369741, 2023).
follicular lymphoma (1 paper, 2009). Follicular lymphoma is a form of non-Hodgkin lymphoma characterized by a proliferation of B cells whose nodular structure of follicular architecture is preserved. "It has been suggested that COL3A1 could be a potential diagnostic marker for large B-cell lymphoma (DLBCL) as is shows statistically significant different expression between DLBCL and follicular lymphoma." (PMID 20043850, 2009).
Gastroesophageal reflux (1 paper, 2017). "COL3A1 variants have also been associated with cerebral aneurysms, gastroesophageal reflux disease, and pelvic organ prolapse." (PMID 28704418, 2017).
gliosarcoma (1 paper, 2019). A rare histological variant of glioblastoma (WHO grade IV) characterized by a biphasic tissue pattern with alternating areas displaying glial and mesenchymal differentiation (WHO). "When compared to GBMs, gliosarcomas show up-regulation of some genes, ranging up to a 6-fold difference on a log2-scale and most top differentiating genes encode collagens (COL1A1, COL6A1, COL6A2, COL6A3, COL1A2, COL3A1)." (PMID 30818875, 2019).
hereditary disorder of connective tissue (1 paper, 2007). An inherited genetic disorder that affects the connective tissues. "Similarly, when no mutation of the COL3A1 gene has been identified, the possible existence of yet unidentified hereditary disorders of connective tissue causing arterial aneurysms or dissections, and therefore mimicking EDS type IV, should be considered." (PMID 17640391, 2007).
Hyperglycemia (1 paper, 2018). An increased concentration of glucose in the blood. "Together, these findings suggest that suppression of miR29c in energy homeostasis related tissues, as a response to hyperglycemia and hyperlipidemia, may play a part in goose fatty liver by modulating energy metabolism via its target genes, Insig1, Sgk1 and Col3a1." (PMID 30400792, 2018).
hyperuricemia (1 paper, 2014). An abnormally high level of uric acid. "The expression of COL3A1, the gene codifying type 3 collagen, is not altered by hyperuricemia, P = 0.674." (PMID 25276832, 2014).
hypospadias (1 paper, 2025). Hypospadias is the displacement of the urethral meatus on the ventrum of the penis. "Therefore, this study aims to investigate the distinct histopathological profiles and expression of COL1A1 (collagen type 1), COL3A1 (collagen type 3), and ELN (elastin) in proximal and distal ventral dartos of patients with hypospadias compared to those with a normal penis." (PMID 39964742, 2025). "This study aims to investigate the distinct histopathological profiles and expression of COL1A1 (collagen type 1), COL3A1 (collagen type 3), and ELN (elastin) in proximal and distal ventral dartos of patients with hypospadias compared to those without hypospadias." (PMID 39964742, 2025).
Intellectual disability (1 paper, 2024). "Five children underwent genetic testing because 1 of their parents was diagnosed with vEDS, 2 because of facial appearance or features consistent with vEDS, and 1 underwent a genetic test for intellectual disability (a de novo deletion of the complete COL3A1 gene)." (PMID 38623759, 2024).
joint disease (1 paper, 2019). "Therefore, collagen dysfunction could lead to bone and joint disease including OA.COL24A1, COL5A2, COL3A1, COL6A1 are members of the collagen gene family." (PMID 30941059, 2019).
knee osteoarthritis (1 paper, 2022). "A previous study showed that Β2-MG treatment of chondrocyte cells taken from knee osteoarthritis patients promoted COL3A1 expression." (PMID 36514703, 2022).
Krebs 2 carcinoma (1 paper, 2022). "The obtained data confirmed the strong overexpression of Mreg, Prg4, Col3a1, Selp, Marco, and Fgfr1 genes in Krebs-2 carcinoma, as well as Cdh11, Col4a5, Vcam1, Megf6, Scarf2, Scart1, and Cd14 genes in HH47." (PMID 36555446, 2022).
lung diseases (1 paper, 2015). "The opposite effect on several genes between mice and humans raises caution on the using mouse model for the study of COL3A1 relevant lung diseases in humans." (PMID 26151842, 2015). "Difference in the molecular pathway of key genes in the COL3A1 gene network in humans and mice suggest caution should be used in extrapolating results from models of human lung diseases in mice to clinical lung diseases in humans." (PMID 26151842, 2015).
malignant astrocytomas (1 paper, 2020). "In addition, the close association observed here between increased VEGFA and COL1A2, COL3A1 and COL1A1 expression in GBM, might also contribute to explain the effect of VEGFA on inducing collagenase expression and remodeling the tumor microenvironment in malignant astrocytomas (i.e. GBM)." (PMID 32647207, 2020).
Menorrhagia (1 paper, 2013). Prolonged and excessive menses at regular intervals in excess of 80 mL or lasting longer than 7 days. "Because ULs and PDCD are both types of fibroproliferative disorders, COL3A1 is thus a candidate for further studies that should evaluate its correlation with Clostridium histolyticum therapy and menorrhagia in UL patients." (PMID 23483937, 2013).
mesothelioma (1 paper, 2021). A usually malignant and aggressive neoplasm of the mesothelium which is often associated with exposure to asbestos. "Mutations in COL3A1 are associated with the development of mesothelioma." (PMID 34691289, 2021). "Also, the prognosis of mesothelioma is associated with COL3A1, COL4A1, and COL15A1." (PMID 34691289, 2021).